DES (desmin)
Diseases named in the same sentence as DES in open-access papers (continued):
Sharing a sentence is not in itself a finding about the gene and the disease.
melanoma (60 papers, 2007 to 2025). A malignant, usually aggressive tumor composed of atypical, neoplastic melanocytes. "The immunohistochemistry results for alpha-smooth muscle actin, desmin, and human melanoma black (HMB)-45 were positive, and those for c-kit and S100 were negative, thus confirming the diagnosis of a PEComa." (PMID 40099082, 2025). "All tumors underwent routine IHC to confirm the LMS diagnosis utilizing smooth muscle markers (SMA, desmin, or H‐caldesmon) and melanoma markers (HMB45, Melan A) to exclude PEComa." (PMID 39691991, 2025). "Hematolymphoid markers (CD45, B cell, and T cell), myogenic markers (myoglobin, desmin, myogenin), melanoma markers (HMB 45, melan A, tyrosinase) and Ewing’s sarcoma markers (CD99/MIC2) are absent in most ONB cases." (PMID 36452830, 2022). "In one study, desmin expression was found in 24% of cases of melanoma, typically confined to only a small number of cells." (PMID 34449584, 2021). "Later on, a few cases of desmin-positive melanomas have been reported, including some exhibiting smooth or skeletal muscle differentiation." (PMID 34449584, 2021). "Immunomarkers, such as chromogranian and synaptophysin, Melan A and HMB45 or desmin and smooth muscle actin, are applied to differentiate neuroendocrine, melanoma and smooth muscle tumors, respectively." (PMID 32867094, 2020). "Cells did not express Pan Cytokeratin AE1 and AE3 (carcinoma marker) and PS100 (melanoma marker) and had a strong expression of desmin and a focal expression of myogenin." (PMID 32438562, 2020). "Our case was S100 positive and negative for cytokeratins (excluding spindle cell carcinoma), smooth muscle markers (desmin, myogenin, and smooth muscle actin, excluding a smooth muscle tumour), and melanoma markers (HMB45 and Melan A)." (PMID 27672465, 2016). "We currently set out to investigate the status of pericytes in the Shb +/− melanomas by staining for the pericyte marker desmin." (PMID 25885274, 2015). "We also noted absence of immunostain positivity for muscle markers (smooth muscle actin, desmin and myogenin), neural and melanoma marker (S-100), pankeratin (AE1/AE3), cytokeratin (CK5/6), CD57 and p63." (PMID 24715974, 2014). "Muscle markers (smooth muscle actin, desmin and myogenin), neural and melanoma marker (S-100), epithelial markers (AE1/AE3), CD57, CK5/6 and p63 were negative." (PMID 24715974, 2014). "Using RT-PCR, we searched for the presence of murine muscle specific transcripts and detected the presence of murine Desmin (an early myogenic marker) suggesting the phenotypic conversion of the melanoma cells into a myogenic lineage upon fusion." (PMID 20174581, 2010). "Immunofluorescent staining illustrated that the CD31 (marker of blood vessels) coverage was lower after JP1 treatment; however, the α-SMA (marker of mural cells), claudin 5 (marker of endothelial cells), and desmin (marker of pericytes) coverage was higher after JP1 treatment in melanoma." (PMID 37192004, 2023). "Indeed, malignant melanomas have been known to express a wide variety of markers including cytokeratin, desmin, smooth muscle actin, amongst others." (PMID 35639915, 2022). "LAM cells consist of two types of cell subpopulations, fibromyoblast-like spindle-shaped cells which express smooth muscle specific proteins (e.g. α‐actin, desmin, vimentin) and epithelioid-like cells which express glycoprotein gp100, a marker of melanoma cells and immature melanocytes." (PMID 33119872, 2021). "These desmin-expressing melanomas are located in the head and neck." (PMID 32670437, 2020). "Further, 10 of the other 10 unspecified melanomas were positive for desmin." (PMID 32670437, 2020). "Desmin is reported to be expressed in osteoblastic melanoma." (PMID 32670437, 2020). "Of the nine proliferative melanomas, seven were positive for desmin." (PMID 32670437, 2020).
melanoma (continued). "However, once the MSCs were within the tumor microenvironment, the expression of α-SMA and desmin was evident, with more positive cells in the plugs containing lal+/+ MSCs and B16 melanoma cells than those containing lal−/− MSCs and B16 cells." (PMID 27531897, 2016). "However, the tumor cells were negative for NFP (neurofilament protein), CD34, desmin, actin, chromogranin, synaptophysin, and pan-melanoma." (PMID 23320233, 2012). "Furthermore, upon fusion with human myogenic cells (CHQ), the B16-GFP cells express early murine myogenic markers such as Desmin suggesting the reprogramming and conversion of melanoma cells into myogenic cells." (PMID 20174581, 2010). "Desmin-expressing melanoma may be diverse in immunophenotype and ultrastructure." (PMID 32670437, 2020). "LMS typically expresses smooth muscle markers (desmin, SMA) and lacks expression of CD117, DOG1, CD34, and S100, helping distinguish it from GISTs, sarcomatoid carcinomas, and melanomas." (PMID 41281033, 2025). "An initial panel of markers should be done to identify the lineage of tumor: carcinoma (cytokeratin AE1/3, OSCAR, CAM5.2), lymphoma (CD20, CD3), melanoma (S-100 protein, SOX10), and sarcoma (desmin, smooth muscle actin, MDM2, ERG)." (PMID 39634259, 2024). "On IHC, tumour cells were positive for S-100 and vimentin, while negative for cytokeratin, epithelial membrane antigen (EMA), desmin, CD34, Melan-A, and human melanoma black (HMB-45)." (PMID 33520482, 2020). "The cells were negative for p63, AE1/AE3, CAM5.2, smooth muscle actin, desmin, human melanoma black-45, and preferentially expressed antigen in melanoma." (PMID 40933634, 2025). "Other pertinent negative immunostains include hematolymphoid markers (CD45, CD3, CD20, CD79a), myoid markers (smooth muscle actin (SMA), desmin), vascular markers (CD31, CD34), epithelial markers (EMA, keratins), melanoma markers (melanA, SOX10, HMB45, S100), and other markers (ALK, CD30)." (PMID 40563703, 2025). "Besides, the presence of multiple malignant somatic components attributable to melanoma (SOX10+, MART1+, HMB45+, VIM+, S100+/-), leiomyosarcoma (alpha-actin+,desmin+), and PNET (CD99+, αFP+) was documented." (PMID 39605889, 2024). "When reviewing the immunohistochemical profile of all reported rhabdoid primary melanomas, regardless of metastasis only two turned out to express desmin while six were negative." (PMID 35645230, 2022). "Furthermore, immunostaining and quantitation of histological sections for perivascular markers, Desmin and αSMA, showed a decrease in tumor perivascular coverage in Vegfr2Cre/+ compared to DFF control mice consistent with our observations in melanoma tumors." (PMID 30283071, 2018). "Spindle and epithelioid cell morphology with some degree of pleomorphism and increased mitotic count raised a suspicion of sarcoma or melanoma, but immunohistochemistry including desmin, CD 99, calretinin, and Melan-A was not supportive." (PMID 27747121, 2016). "Interestingly, aberrant desmin expression was a frequent finding in S100 protein negative melanomas, present in three of five such cases." (PMID 34449584, 2021). "However, staining was negative for CD34, desmin, S-100 protein, cytokeratin, human melanoma black (HMB)-45, B-cell lymphoma (Bcl)-2 and CD99." (PMID 24348865, 2014). "Immunohistochemically, the tumor cells were positive for S100 (5/6), cyclin D1 (2/3), SATB2 (2/3), BCOR (2/4), and TLE1 (1/3) while negative for MUC4 (0/6), keratin (0/5), EMA (0/4), desmin (0/6), CD34 (0/6), SMA (0/5), SOX10 (0/5), and pan melanoma (0/2)." (PMID 40705064, 2025). "S100, desmin, and SMA (smooth muscle actin) were not defined in any case, so the diagnosis of smooth muscle tumors and melanomas was excluded." (PMID 39502983, 2024). "Histopathology showed the presence of melanoma cells (HMB45+, SOX10+, desmin-, panCK-) with a negative immunohistochemistry for V600E BRAF mutation and positive for c-Kit." (PMID 39605889, 2024).
melanoma (continued). "Melanoma, on the other hand, is typically positive for c-kit, CD68, S-100, HMB-45, Melan-A, throsinase, and vimentin, and negative for smooth muscle actin, desmin, chromogranin, and epithelial membrane antigen." (PMID 33478436, 2021). "Immunohistochemistry stains were positive for desmin, smooth muscle actin (SMA), CD34 and negative for human melanoma black (HMB)-45 antigen and CD117." (PMID 27785206, 2012). "In our two cases, immunohistochemical staining demonstrated that the tumor cells expressed HMB45, S-100, pan melanoma and Vimentin, and did not express CK, EMA, CgA, Syn, HCG, HMW-CK, Desmin, SM-actin, TTF-1, and SCLC." (PMID 22992473, 2012). "Immunohistochemically, the tumor cells were positive for S100 (5/6), cyclin D1 (2/3), SATB2 (2/3), BCOR (2/4), and TLE1 (1/3) while negative for MUC4 (0/6), keratin (0/5), EMA (0/4), desmin (0/6), CD34 (0/6), SMA (0/5), SOX10 (0/5), and melanoma cocktail (0/2)." (PMID 40705064, 2025). "Additionally, the tumor cells were negative for Desmin (arguing against a myogenic tumor), S100 (excluding malignant melanoma and neurogenic tumor), HMB45 (excluding melanoma), and STAT6 (arguing against a solitary fibrous tumor)." (PMID 41584573, 2025). "All other markers tested were negative (pan-melanoma, HMB45, Melan A, keratin AE1/AE3, desmin, alpha smooth muscle actin, h-caldesmon, CD34, p16, CD117, DOG1, myogenin, CD10, estrogen receptor (ER), progesterone receptor (PR), PAX8, WT1, synaptophysin, chromogranin A, CD99 and PRAME))." (PMID 39196362, 2024). "However, staining for myoglobin, desmin, MSA, SMA, human melanoma, black-45 (HMB-45) and CD99 are often negative, which is consistent with the present case." (PMID 23761028, 2013). "Based on α-SMA staining and the ratio of desmin to CD31 expression as markers of tumor blood vessel functionality, we found evidence for increased stabilization of colorectal microvessels, but no such change in melanoma vessels." (PMID 21159176, 2010). "Malignant melanoma, GIST, MPNST, sarcomatoid renal cell carcinoma, and malignant fibrous histiocytoma will be positive for vHMB-45, c-kit, S-100, RCC marker, and CD68, respectively, and will be negative for desmin, synaptophysin, inhibin, Melan-A, and calretinin." (PMID 25685588, 2015).
sarcoma (52 papers, 2007 to 2025). A usually aggressive malignant neoplasm of the soft tissue or bone. "The tumor’s mesenchymal origin necessitates the demonstration of smooth muscle differentiation through positivity for SMA, desmin, and caldesmon, while excluding other sarcoma subtypes and metastatic disease." (PMID 40666089, 2025). "GCTs are usually negative for cytokeratin (Cam 5.2 and AE1/AE3), vimentin and desmin, which are epithelial and sarcoma antigens." (PMID 38959614, 2024). "A study on 28 SFT cases found that INSM1 was reactive in 21% (6/28) of the cases, which was slightly superior to desmin (14.3%, 4/28) and p16 (17.9%, 5/28), suggesting differential diagnosis of sarcomas can be supplemented by the use of the INSM1 marker." (PMID 36531655, 2022). "RST/Myo hybrids express desmin and transgelin, so the resulting tumours are classified as undifferentiated pleomorphic sarcomas with an incomplete muscular differentiation." (PMID 33303824, 2020). "Positivity of α-SMA and negativity of desmin, taken together, are able to conclude the diagnosis of these three cases as myofibroblast-rich sarcoma." (PMID 31653220, 2019). "Immunohistochemistry is critical to making the diagnosis of SCUP since these cases often express both broad lineage carcinoma (pancytokeratin) and sarcoma (vimentin and desmin) markers." (PMID 31623602, 2019). "Around the sarcoma were a concentration of myofibroblasts marking with desmin and smooth muscle actin (SMA), and overall the background tissues were prominently fibrotic." (PMID 29152519, 2017). "Undetermined tumours should be subjected to further immunohistochemistry, such as analysis of smooth-muscle actin, desmin, vimentin, von Willebrand factor or neuron-specific enolase, before a final diagnosis of “poorly differentiated sarcoma” should be made." (PMID 25563490, 2015). "Immunohistochemical studies revealed diffuse positivity with S-100 protein, and negativity with Desmin and Vimentin, thus consistent with granular cell tumor instead of the suspected sarcoma." (PMID 17355632, 2007). "Reactivity for vimentin, desmin, muscle specific actin and S-100 protein was observed in poorly differentiated areas in addition to the expected positivity of each histologic subtype of sarcoma." (PMID 33235646, 2020). "Histopathology revealed characteristic GCTs with positive immunostaining for neural marker (S-100) and negative immunostaining for epithelial (cytokeratin, Cam 5.2, AE/A13), neuroendocrine (neuron specific enolase, chromogranin A, and synaptophysin) and sarcoma (desmin, vimentin) markers." (PMID 17355632, 2007). "These sarcomas with muscle differentiation are usually positive for muscle markers such as smooth muscle actin (SMA) and/or desmin." (PMID 38900740, 2024). "The sarcoma stained focally for SMA, focally for desmin, and showed strong diffuse staining with CD10." (PMID 29152519, 2017). "Eighty-six poorly-differentiated neoplasms were categorized as carcinomas, sarcomas, lymphomas or neuroendocrine cancers with a panel of 7 antibodies (cytokeratin AE1/AE3, vimentin, desmin, myogenin, leukocyte common antigen and neuron-specific enolase)." (PMID 21044352, 2010). "IHC confirmed desmin expression in a substantial subset of PLMS and high-grade sarcoma samples." (PMID 40868997, 2025). "The presence of AE1/AE3 is present in about 97% of carcinomas which differs from their sarcoma counterparts that mainly express desmin and actin, two stains that are predominantly negative in carcinomas." (PMID 39564030, 2024). "In IHC, undifferentiated cells typically express broad lineage carcinoma (PCK) and sarcoma (vimentin and desmin) markers and exhibit the absence of E-Ca." (PMID 38389041, 2024). "In addition, decisive immunohistochemistry markers for undifferentiated pleomorphic sarcoma include S100/SOX10, smooth muscle actin (SMA), and desmin." (PMID 37635229, 2023).
sarcoma (continued). "In two poorly differentiated sarcomas, tumour cells expressed Iba-1 and vimentin (clone V9) and were negative for desmin and α-SMA, so they were reclassified as histiocytic sarcomas." (PMID 35454212, 2022). "Common immunochemical markers for sarcoma are vimentin, keratin, desmin, leucocyte common antigen, and S100, but not CD99 and MIC2, which characterize primitive neuroectodermal components, a hallmark of immature teratomas." (PMID 27528018, 2016). "CD45, CD20, CD79a, and PAX5 should be positive in DLBCL as in our case, while other markers for sarcoma including smooth muscle actin, muscle specific actin, and desmin should be negative." (PMID 25984371, 2015). "Additionally, 6 of the 10 PLMS cases exhibited a myostatin-negative/desmin-positive (diffuse or focal) phenotype, while 7 of the 17 high-grade sarcomas displayed a myostatin-positive (diffuse)/desmin-negative (or very focally positive) phenotype." (PMID 40868997, 2025). "In our case, histopathological examination revealed the same morphological appearance, with low Ki-67 expression (<1 %), rare mitoses, and myofibroblastic differentiation (vimentin/SMA/desmin positive, S100 negative), ruling out high-grade sarcoma and neurogenic tumors." (PMID 40674963, 2025). "Immunohistochemistry tests for desmin, vimentin, α‐SMA, CK, leukocyte common antigen (LCA), CD34, human melanoma black 45 (HMB45), epithelial membrane antigen (EMA), and S100 are performed in sarcomas to differentiate other tumor types and make a final diagnosis." (PMID 36093467, 2022). "In addition to being positive for vimentin, these sarcomas may be positive for either SMA and/or desmin, resulting in desmin(+)/SMA(−), desmin(−)/SMA(+) and desmin(+)/SMA(+) immunophenotypes." (PMID 25624890, 2015). "Various markers, such as desmin, S100protein, CD31, CD34, epithelial membrane antigen (EMA), cytokeratin, and E-cadherin, are used to rule out other types of sarcomas." (PMID 41446455, 2025). "Since CD34 is a marker for lipomas and lipoma-like sarcomas, further analysis of SCL typically shows negative staining for desmin, RB1, MDM2, and SMA." (PMID 40980795, 2025). "In poorly differentiated sarcomas, tumour cells expressed vimentin (clone V9) and α-SMA and were negative for Iba-1 and desmin." (PMID 35454212, 2022). "In the poorly differentiated sarcoma, tumour cells expressed vimentin (clone 3B4) but were negative for Iba-1, α-SMA and desmin." (PMID 35454212, 2022). "Staining for S100, actin, caldesmon, desmin, and CD34 was focal and nonspecific, indicating that the tumors could not be assigned to a particular differentiated sarcoma subtype." (PMID 37332046, 2023).